UBE2J2 (ubiquitin conjugating enzyme E2 J2)
Description:
Catalyzes the covalent attachment of ubiquitin to other proteins. Seems to function in the selective degradation of misfolded membrane proteins from the endoplasmic reticulum (ERAD) (By similarity). In cooperation with the GATOR2 complex, catalyzes 'Lys-6'-linked ubiquitination of NPRL2.
Synonyms: NCUBE-2; NCUBE2; Ubc6p; PRO2121; UBC6
Tractability: Antibody: UniProt predicts a signal peptide or a membrane-spanning region. PROTAC: UniProt records ubiquitination sites on it; ubiquitination databases record sites on it.
Gene: Protein-coding gene on chromosome 1 (1,253,907 to 1,274,477, reverse strand). Ensembl gene ENSG00000160087.
Subcellular location: Endoplasmic reticulum membrane
Pathways (Reactome):
Immune System: Antigen processing: Ubiquitination & Proteasome degradation
Metabolism of proteins: E3 ubiquitin ligases ubiquitinate target proteins
Protein localization: Insertion of tail-anchored proteins into the endoplasmic reticulum membrane
Gene Ontology:
Molecular function: protein binding; ubiquitin conjugating enzyme activity; ubiquitin protein ligase binding
Biological process: ERAD pathway; positive regulation of establishment of protein localization to mitochondrion; protein K6-linked ubiquitination; ubiquitin-dependent protein catabolic process; protein polyubiquitination; protein ubiquitination
Cellular component: ubiquitin ligase complex; cytosol; endoplasmic reticulum; endoplasmic reticulum membrane
Genetic constraint (gnomAD): Loss-of-function variants: 2 observed, 20.54 expected, observed/expected ratio (o/e) 0.0974, 90% interval 0.039 to 0.31. The upper end of that interval is the gene's LOEUF score, 0.31, which puts it in group 1 of 6, group 1 being the genes least tolerant of losing a copy. Missense variants: 186 observed, 304.68 expected, observed/expected ratio (o/e) 0.61, 90% interval 0.54 to 0.69. Synonymous variants: 120 observed, 126.52 expected, observed/expected ratio (o/e) 0.95, 90% interval 0.82 to 1.1.
Homologues: Orthologues: chimpanzee UBE2J2 (99% identical), guinea pig UBE2J2 (96% identical), pig UBE2J2 (95% identical), rat Ube2j2 (95% identical), mouse Ube2j2 (94% identical), rabbit UBE2J2 (92% identical), zebrafish ube2j2 (88% identical), tropical clawed frog ube2j2 (81% identical), dog UBE2J2 (76% identical), macaque UBE2J2 (62% identical), Drosophila melanogaster CG5823 (57% identical), Caenorhabditis elegans ubc-26 (46% identical), and 1 more. Paralogues in human: UBE2J1 (33% identical), CDC34 (19% identical), UBE2K (17% identical), UBE2N (17% identical), UBE2A (16% identical), UBE2B (16% identical), UBE2R2 (16% identical), UBE2Z (16% identical), UBE2G1 (16% identical), UBE2T (16% identical), UBE2G2 (15% identical), UBE2NL (15% identical), and 12 more.
Diseases named in the same sentence as UBE2J2 in open-access papers:
UBE2J2 is named in the same sentence as 13 diseases in open-access papers, as found by Europe PMC text mining. Sharing a sentence is not in itself a finding about the gene and the disease. The quoted sentences say what the papers report.
hepatocellular carcinoma (3 papers, 2017 to 2022). A malignant tumor that arises from hepatocytes. "The UBE2J2 protein is expressed in most hepatocellular carcinoma (HCC) tissues, especially in metastatic HCC tissues." (PMID 34199813, 2021).
cytomegalovirus infection (2 papers, 2020 to 2022). A herpesvirus infection caused by Cytomegalovirus. "However, sgRNAs targeting UBE2J2 resulted in further downregulation of HLA-A2 expression, suggesting that UBE2J2 counteracts the downregulation of HLA class I by US2 during HCMV infection." (PMID 32587832, 2020).
Azoospermia (1 paper, 2025). Absence of any measurable level of sperm,whereby spermatozoa cannot be observed even after centrifugation of the semen pellet. "It is highly plausible that a human family could carry mutation in Ube2j2 gene that manifests as azoospermia." (PMID 40686610, 2025). "We found that deletion of Ube2j2 results in azoospermia in male mice and spermatocyte meiosis is arrested in the mid-pachytene stage." (PMID 40686610, 2025). "Our results show that male mice lacking UBE2J2 display azoospermia, with meiotic arrest occurring in the mid-pachytene stage of spermatocyte development." (PMID 40686610, 2025).
HIV-1 infection (1 paper, 2025). The type species of lentivirus and the etiologic agent of acquired immunodeficiency syndrome (AIDS). "While UBE2L6 is a known ISG15 ligase in innate immune response, UBE2J2 has no documented role in HIV-1 infection." (PMID 40204275, 2025).
renal cell carcinoma (1 paper, 2023). "These 27 CTTs including 8 genes CTNNA1, PSMB6, PSMD12, SESN2, SLC22A2, UBE2J2, and NAE1 appeared in the SL pairs of renal cell carcinoma in previous literature studies." (PMID 38074121, 2023).
cancer (4 papers, 2020 to 2024). A tumor composed of atypical neoplastic, often pleomorphic cells that invade other tissues. "Using a CRISPR/Cas9-based approach, UBE2J2 was identified as the primary ERAD-associated E2 enzyme that is essential for the MARCH6-dependent degradation of SQLE, and disturbance of cholesterol-accelerated SQLE degradation was observed when ablating UBE2J2 in multiple human cancer cell types." (PMID 38612682, 2024). "We identified two genomically co-localized signatures, UBE2J2 and MIIP located on 1p36.33-36.22 that have not been detected as pan-cancer deleted regions." (PMID 33057153, 2020).
tumor (3 papers, 2014 to 2025). "Immunohistochemical analyses showed that UBE2J2 was expressed at higher levels in HC patient tissues than in corresponding non-tumor tissues." (PMID 29069742, 2017). "Positive UBE2J2 staining (score >2) was detected in 42/45 (93.3%) metastatic HC samples, and 13/45 (28.9%) corresponding non-tumor tissues, (P<0.01)." (PMID 29069742, 2017). "IHC analyses showed UBE2J2-positive staining in most HC tissues compared with corresponding non-tumor tissues, indicating that UBE2J2 might be a useful biomarker for HC diagnosis." (PMID 29069742, 2017).
UBE2J2 also shares sentences with these, for which no sentence is quoted: acute myeloid leukemia (1 paper); autoimmune disease (1); coronary heart disease (1); inflammatory bowel disease (1); neuroblastoma (1); ulcerative colitis (1).